IFNG (interferon gamma)
Diseases named in the same sentence as IFNG in open-access papers (continued):
Sharing a sentence is not in itself a finding about the gene and the disease.
infection (continued). "Of these, Il18 is reported to interact with Il12 to stimulate interferon gamma (IFN-γ) production from NK cells during the early host response to infection." (PMID 26779389, 2015). "As reviewed elsewhere, IFNγ can contribute to the protection against infection with some viruses, such as hepatitis B virus, herpes simplex virus, and lymphocytic choriomeningitis virus." (PMID 26345454, 2015). "In this study, we show that lung parenchymal cells express immunoproteasomal subunits at low basal levels, but they can be rapidly induced to form active immunoproteasomes upon IFNγ stimulation in vitro or MHV-68 infection in vivo." (PMID 25989070, 2015). "Orchidectomy at day 60 post-infection produced a significant decrease of bacilli burdens in coexistence with higher expression of TNFα, IL-12 and IFNγ." (PMID 24722144, 2014). "A similar tendency of reduced tet-gp33+ CD8+ T cells and reduced IFNγ production was also seen on day 6 post-infection." (PMID 25333902, 2014). "Next, we quantified not only single meronts, but also meronts that had replicated by binary fission (double meronts) and compared uninduced to IFNγ-induced MEF cells 24 hours post infection." (PMID 25356593, 2014). "The same study showed that HLA-C1 inhibited NK cells are better able to mount rapid, intense responses to infection through degranulation and IFNγ secretion." (PMID 24651768, 2014). "iNKT cells localize to the inflamed heart, enhancing macrophage phagocytosis through IFNγ leading to control of infection." (PMID 24904837, 2014). "With the growing understanding of the roles that cytokines play in infection and disease progression, cytokines including IFNγ have been measured to assess the efficacy of anti-retroviral therapy (ART)." (PMID 24454311, 2014). "A smaller proportion of IFNγ+CD44highCD4+ medLN Th1 cells was detected in Cd28flox/floxOx40cre/+ mice at 7 days post infection, just after the reported peak of CD4+ T cell expansion." (PMID 25347065, 2014). "Animal models and in vitro studies have shown that IFNγ is a key effector cytokine required for control of the infection, however, the role of endogenous IFNγ in control of parasites in VL patients, has not been demonstrated." (PMID 25275531, 2014). "Depletion of CD4 cells from ex vivo SA cultures support these cells as the source of IFNγ at the site of infection." (PMID 25275531, 2014). "Only 2 of the 8 subjects reached IFNγ levels comparable to those exhibited by Subject A after primary infection." (PMID 25397604, 2014). "Most patients with VL have antigen specific CD4 T cells capable of secreting IFNγ both in the blood and at the site of infection - the spleen." (PMID 25275531, 2014). "The only clear observed strain-specific difference was a higher IFNγ level 6 hrs post infection in BALB/c than in C57BL/6 serum." (PMID 24967701, 2014). "Our data demonstrate a consistent pattern of pro-inflammatory cytokine production by C. jejuni-specific CD4+ T cells following primary infection, which included IFNγ, TNF-α, IL-2, and the chemokine, MIP-1β." (PMID 25397604, 2014). "Inflammation (IL-12, IFNα/β, IFNγ, and chemokines) at the site of infection then results in expansion of resident cells and recruitment of peripheral NK cells which provide additional protection." (PMID 25197644, 2014). "The importance of IFNγ was noted early in response to vaginal infection of mice with HSV-2 where it was shown to help in resolving this infection in mice." (PMID 25197644, 2014). "IFNγ can lower bacterial number following infection with LVS, and can reduce the intra-macrophage growth of LVS in a dose-dependent manner." (PMID 24600590, 2014). "Use of IFNγ reporter mice reinforced that such production was largely from NK cells, whereas at late stages of infection, immediately prior to and during neurological disease, CD4+ and CD8+T cells are the predominant sources." (PMID 25177551, 2014).
infection (continued). "This suggests the capacity to synthesize tryptophan in an IFNγ-rich infection microenvironment is an important virulence factor for genital C. trachomatis serovars." (PMID 24918090, 2014). "IL-17A was previously reported to inhibit immigration of NK and other cell types into the site of infection in AD skin and to promote WR replication, while IFNγ reveals immunomodulatory and antiviral properties." (PMID 25486419, 2014). "YopE69–77-immunized mice that completely lack the ability to produce either TNFα or IFNγ succumb to infection, suggesting that each of these cytokines are absolutely required for CD8 T cell-mediated anti-Yersinia immunity." (PMID 24854422, 2014). "Specifically, while pretreatment of macrophages with IFNγ enhanced their ability to clear mycobacterial infections the same treatment, given post-infection, is unable to achieve efficient clearance of the bacterium." (PMID 24885748, 2014). "A recent study evaluated a combined proinflammatory and immunomodulatory cytokine panel including IFNγ to predict viral load set point 12 months after infection." (PMID 24454311, 2014). "During infection, resident mucosal tissue NK cells respond primarily through IFNγ production, which contributes directly to early control of pathogens." (PMID 25197644, 2014). "CR and SJZT alleviated infection-induced interferon-gamma levels in the serum and tissues, and tumor necrosis factor-alpha (TNF-α) levels in intestinal tissues." (PMID 25133542, 2014). "Plasma levels of α-defensins, IL-10 and IFNγ peaked in the acute phase of infection, whereas IL-15 showed fluctuation throughout the study (data not shown)." (PMID 24695530, 2014). "The goals of the current study were to validate the prior WBA results, to reveal the conditions required for SLA induced IFNγ secretion by WB and to determine if the IFNγ seen in patients with active disease functions to limit the infection." (PMID 25275531, 2014). "Secretion of IFN-γ is dependent on IL-18, also known as interferon gamma inducing factor, and is essential for establishing an early host resistance to infection with Salmonella." (PMID 25339955, 2014). "All infected calves had a strong reaction in the interferon-gamma release assay as soon as 3 months after infection and persisting for the duration of the trial." (PMID 25372282, 2014). "Eight days after infection, PbT-I cells harvested from the spleen produced IFNγ, TNFα and CD107a, indicating their development of effector function." (PMID 24854165, 2014). "In order to evaluate the role of antiviral innate immunity following SHIVSF162P4cy infection, the production of cytokines (IL-10, IFNγ, IL-15) and α-defensins were determined in plasma of infected monkeys." (PMID 24695530, 2014). "The detection of IFNγ responses in stimulated splenic aspirate cells indicates that antigen specific and responsive cells are present at the site of infection." (PMID 25275531, 2014). "Manipulation of the immune response during primary infection in the neonate, using the Th1 promoting cytokine IL-18, CpG or IFNγ, reduces pathology following re-infection." (PMID 25324843, 2014). "Splenocytes isolated at 28 days post-infection (dpi) were simulated overnight with 1 μg/ml αCD3 antibody in the presence of monensin to capture intracellular IFNγ production." (PMID 24587276, 2014). "Epitope-defined IFNγ assay kits became established for the specific detection of infection with tubercle bacilli both in humans and cattle." (PMID 24715888, 2014). "Nevertheless, in the absence of Tregs we observed priming of stronger effector T cell responses in the periphery, which subsequently resulted in a transient increase in the frequency of IFNγ-producing T cells in the brain at an early stage of infection." (PMID 25391297, 2014). "Critically, the availability of indole within the infection microenvironment is predicted to modulate the effect of IFNγ." (PMID 24918090, 2014).
infection (continued). "At one day post infection, viability of infected cells was significantly reduced in dependence of IFNγ-induction and this was even more pronounced at 2 days post infection." (PMID 25356593, 2014). "In an HIV-1 infected individual, the production of IFNγ is detected as early as the acute phase and continually detected throughout the course of infection." (PMID 24454311, 2014). "Specifically, at both days 3 and 6 post-infection, IFNG, IL6, TNF, MIP1B and IL10 were all significantly diminished in MYD88-deficient mice as compared to wild-type mice." (PMID 25192715, 2014). "Among mice infected with PR8 at day 2 after infection, IFNG was only expressed in C57BL/6J, CAST/EiJ, PWK/PhJ, and WSB/EiJ, whereas it was expressed in all strains except CAST/EiJ on day 4 after infection." (PMID 24902603, 2014). "This sequence also induced IFNγ production from endogenous T cells and PbT-I T cells responding to blood-stage infection." (PMID 24854165, 2014). "To gain a better understanding of the kinetics of Gbp-mediated cell-autonomous immunity towards C. trachomatis, we activated MEFs with IFNγ at 3 hours post-infection (hpi)." (PMID 24466199, 2014). "Similar to the mRNA expression, protein levels of IL-1β, TNF, IL-6, IFNγ, and IL-1α were also significantly elevated in the brains of db/db mice when compared to WT mice at day 8 after infection as measured by the multiplex immunoassay (P <0.05)." (PMID 24750819, 2014). "For example, human colonic explants infected with C. jejuni exhibited marked increases in IFNγ production following infection." (PMID 25397604, 2014). "In humans, decreases in antibody responses and in the frequency of T. cruzi-induced IFNγ-production by T cells and following benznidazole treatment have provided methods to evaluate infection and treatment efficacy in people." (PMID 24456537, 2014). "Together, the infection experiments in two cultured human cell lines demonstrated that IFNγ is engaged in the protection from T. cruzi infection and, moreover, point to a role of STAT1 in this process." (PMID 25340519, 2014). "In the antigen-pDNA -vaccinated zebrafish, interferon gamma expression levels are significantly higher during infection than in the control pDNA vaccinated fish, demonstrating the specificity of the anti-mycobacterial immune response induced in zebrafish." (PMID 24968056, 2014). "10NOS2−/− mice developed a substantial induration in response to infection, as well as an increased interferon-gamma response to components of the leprosy bacillus." (PMID 25210773, 2014). "IFNγ and IL-10 cytokines were measured in liver and spleen tissue homogenates, as well as in serum samples at 15 weeks post-infection, by ELISA." (PMID 25108307, 2014). "A Th1 response, and in particular interferon γ (IFNγ) production, are essential for the activation of macrophages and the control of infection." (PMID 24405814, 2014). "Infection increased lipid peroxidation and the release of TNFα and IFNγ, although capsazepine-treated group exhibited lower levels of lipid peroxidation and TNFα." (PMID 25242870, 2014). "A knockout mouse lacking both B7-family receptors CD80 and CD86 has severe defects in IFNγ secretion by T cells and the response to secondary infection, in addition to a failure to produce neutralizing antibodies and maintain long-term control of latency." (PMID 24587276, 2014). "The levels of macrophage inflammatory protein 1α (MIP-1α) and interferon gamma (IFN-γ) in spleen were higher 42 h after infection in CpG-treated compared to buffer-treated neutropenic animals." (PMID 24456653, 2014). "The loss of fecundity was accompanied by reduced IFNγ expression by CD4+ T cells and a higher proportion of macrophages at the site of infection." (PMID 24586152, 2014). "IFNγ has been shown both in cell culture and in vivo models to provide protection against infection by C. muridarum and C. psittaci." (PMID 25386180, 2014).
infection (continued). "Our data shows that following primary infection in all subjects, peripheral C. jejuni-specific CD4+ T cells produce pro-inflammatory cytokines, including IFNγ and TNFα, peaking 7-14 days post-infection." (PMID 25397604, 2014). "At all time points examined post-infection, a significantly greater percentage of iNKT cells in the lung produced GM-CSF than IFNγ." (PMID 24391492, 2014). "In explorative experiments, it was observed that splenic and peripheral blood CD8+ KLRG1high, CD27low, CD44high, CD62Llow T cells respond to in vitro stimulation with anti CD3 and in vivo sporozoites infection by producing IFNg." (PMID 24620841, 2014). "Later in infection, FP-inoculated mice initiated a strong T cell response, with significantly higher production of IFNγ, TNFα and IL-2 than IN-inoculated mice." (PMID 24922480, 2014). "WNV infection resulted in a 3- to 10-fold increase in the mRNA expression of cytokines such as IL-1β, TNF and IFNγ in the brains of WT mice at day 8 after infection compared to corresponding mock-infected mice." (PMID 24750819, 2014). "In human genital infections, local cervical T-cell infiltrates and genital IFNγ concentrations are significantly elevated during active infection, higher in women with recurrent vs. primary infection, and decreased upon resolution of infection, and." (PMID 24918090, 2014). "Increased IFNγ is observed at the site of infection of cattle during the excretory, subclinical stage of JD, and increased production of IFNγ has been reported after stimulation of peripheral blood mononuclear cells (PBMCs) with MAP antigens." (PMID 26664912, 2014). "Gavage infection resulted in high levels of IFNγ, CCL2 and IL-6 already at day 2, followed by the gradual decrease of these cytokines." (PMID 25919005, 2014). "Systemic production of interferon gamma (IFN-γ) is induced during infection and regulates the production of matrix metalloproteinases (MMPs) and their inhibitors (TIMPs), both important in plaque stability." (PMID 23951304, 2013). "Additional approaches currently being evaluated include assessing cytokine profiles in the blood of patients in the acute phase of enteric fever, or cellular responses during the acute stage of infection, including assessing interferon-gamma release assays." (PMID 23951368, 2013). "Interferon gamma is not secreted in a vacuum; IL-10 and other Th2 cytokines exert critical effects on IFN-γ both at the level of induction and at the level of effector function, which then determine the course of infections." (PMID 23801993, 2013). "Electrophoretic mobility shift assays (EMSAs) revealed the presence of an aberrant GAS-binding complex that increased during the infection period in the presence of IFNγ." (PMID 23527309, 2013). "In Section 2, we describe the experimental and mathematical methods employed to determine enzyme and metabolite levels in response to infection and IFNγ treatment and to model the pathway." (PMID 22664637, 2013). "Immunophenotyping results showed a pronounced increase of IL-17A- and IFNγ-producing cells in the gastric LP after 30 and 60 days post-infection." (PMID 24039925, 2013). "A strong cell-mediated immune (CMI) inflammatory response, involving tumor necrosis factor-alpha (TNF-α) and interferon-gamma (IFN-γ), is rapidly induced by infection with MTC and is required to protect the infected host against TB." (PMID 23593415, 2013). "Mechanisms proposed to explain the detrimental actions of IFN-I signalling after i.p. infection are increased T lymphocyte and macrophage death and unresponsiveness of macrophages to IFNγ." (PMID 23840314, 2013). "Susceptibility to infection was observed in patients with the IFNG +874A/A genotype, which characterized the low producer phenotype of IFN-γ and was more frequent among patients compared with controls." (PMID 23936772, 2013).
infection (continued). "For example, the proinflammatory cytokine IFNγ is produced by macrophages following intracellular invasion and is known to prime macrophages to respond to infection." (PMID 23460923, 2013). "Despite their enhanced survival, bim−/− SMARTA cells demonstrated consistently poor functionality throughout the effector and memory phases following Lm-gp61 infection, largely solely producing IFNγ." (PMID 23840678, 2013). "Salmonella-specific IFNγ+ Tbet+ CD4 T cells were first detected at 8 days post-infection and expanded continuously through 30 days post-infection." (PMID 23754944, 2013). "At the time of FV superinfections (around 35 days post mCMV infection) enhanced IFNγ levels were detectable only in a few persistently mCMV infected mice and the overall difference between naïve and mCMV infected mice was not significant (data not shown)." (PMID 23738889, 2013). "IFNγ-producing DC have been identified in few other adult mouse models of infection or gastrointestinal inflammation." (PMID 24367259, 2013). "Production of IFNγ is mostly regulated by two other cytokines such as IL-12 and IL-18 which mediate IFNγ production upon infection with Mtb in cellular innate immune response." (PMID 24350246, 2013). "qRT-PCR results revealed significant (p<0.05) induction of IL-1β, IL-2, and IFNγ transcription, with the greatest induction observed upon infection with the chicken-origin isolate." (PMID 23521892, 2013). "Increased expression of IFNγ, IL-10, and FOXP3 has been associated with longer episodes of infection." (PMID 23457650, 2013). "Although IFNγ is required for host defense, the response must also be partially counteracted to allow persistent life-long infection." (PMID 23527309, 2013). "At 4 weeks post infection, IFNγ, IP-10, MIG, MCP-1, IL-17 and IL-6 were elevated in infected mice compared to the uninfected mice." (PMID 23469125, 2013). "In other animal models, studies in S. Typhimurium-infected swine uncovered positive correlations between early fecal shedding of salmonella (within the first week of infection) with increased neutrophil numbers and high serum IFNγ." (PMID 23754944, 2013). "Adult mice in which IFNγ expression or its signalling are affected such as IFNγ−/− or STAT-1−/− mice display high sensitivity to the infection and long-term carriage of the parasite." (PMID 24367259, 2013). "Conjunctival gene expression profiling in children with active disease and Ct infection found an increase in both Th1 (IFNγ) and Th2 (IL-4) cytokine expression." (PMID 23457650, 2013). "To determine biological significance, we infected mice with Leishmania major, as pathogen clearance is highly dependent on IFNγ-producing CD4+ T cells at the infection site." (PMID 23991011, 2013). "The serum levels of IFNγ were elevated by four days post-infection and remained consistently high during the first month of infection." (PMID 23754944, 2013). "Production of IL-12, and subsequently IFNγ, upon infection triggers host immunity that prevents early dissemination of pathogenic intracellular pathogens." (PMID 24068935, 2013). "To compare modulation of the pathway in response to IFNγ with its modulation in response to infection, we next modelled the pathway activity using the time course recorded in response to mCMV infection." (PMID 22664637, 2013). "CD11c+MHCII+CD103+ cells isolated from the small intestine of infected (6 dpi) and uninfected age-matched controls were stained for IFNγ and this confirmed that a fraction of CD103+DC do indeed produce IFNγ during infection." (PMID 24367259, 2013). "Infection of IFNγ-prestimulated astrocytes with the type II strains ME49 or NTE resulted in a significant reduction to 5 or 6 tachyzoites per cell." (PMID 24324375, 2013). "It was proposed that LPS, as well as IFNγ produced during the course of infection, activates microglia and astrocytes, thereby resulting in damaged oligodendrocytes in PVL." (PMID 24244457, 2013).